RAC1 (Rac family small GTPase 1)
Diseases named in the same sentence as RAC1 in open-access papers (continued):
Sharing a sentence is not in itself a finding about the gene and the disease.
cancer (continued). "Recently, Rac1 is reported to be required for efficient NDV replication in human cancer cells and established a link between tumourigenesis and sensitivity to NDV." (PMID 23586025, 2013). "The induction of Rac1 activity by the guanine nucleotide exchange factor (GEF) Vav2 causes invasion and contributes to cancer cell survival and disruption of correct polarisation of the breast epithelium." (PMID 22689141, 2012). "Our results show that loss of miR-204 promotes BDNF (or EGF)-induced cancer cell migration and invasion by activating AKT/mTOR pathway leading to Rac1 translocation and actin reorganization." (PMID 23285024, 2012). "Rac1, a member of the Rho family of small GTPases plays crucial roles in the reorganization of actin cytoskeleton and motility, and inhibition of Rac1 or its downstream effectors severely impairs cell migration and dissemination of cancer cells." (PMID 22384062, 2012). "Rac1 is well-known required for the progression and metastasis of cancer cells by mediating growth factor-induced motility and invasiveness." (PMID 22701712, 2012). "It has been shown that the expression of MMPs was regulated by small Rho GTPases (Cdc42, Rac1 and RhoA), which are involved in many normal and pathological cellular processes, including cancer invasion and metastasis." (PMID 22610942, 2012). "Our findings reveal that loss of miR-204 results in BDNF/TrkB overexpression and concomitant activation of the AKT/mTOR/Rac1 signaling pathway, leading to actin reorganization during cancer cell migration and invasion." (PMID 23285024, 2012). "Given that inhibitors are being developed to target Rac effector proteins such as PAK kinases or to block Rac activation, these results provide compelling target validation of Rac1 in Ras-driven cancers." (PMID 21358804, 2011). "RhoA is frequently overexpressed in cancer, while depletion of Rac1 strongly inhibits lamellipodia formation, cell migration and invasion in carcinoma cells." (PMID 21943101, 2011). "In particular, the role of RhoA (Ras homolog gene family, member A), Rac1 (Ras-related C3 botulinum toxin substrate 1) and Cdc42 (cell division cycle 42) in cancer progression induced by each of the three oncogenes is described." (PMID 21943101, 2011). "More specifically, Rac1 aids cancer cells to more efficiently antagonize TGF-β1/Smad3-mediated growth inhibition via its ability to promote Smad2 activation." (PMID 21624123, 2011). "Rac1 has a critical role in cell migration, and in the invasive, and metastatic behavior of cancer cells." (PMID 21624123, 2011). "ARHGAP19 is a member of a family of GTPase activating proteins, and other family members, 8, 9, 12 and 15, are expressed in several types of cancer and activate Cdc42, Rac1 or RhoA, small GTPases required for migration." (PMID 21501518, 2011). "As expected from its cell cycle activating function in other carcinoma cells, Rac1 depletion attenuated basal growth of cells cultured in normal growth medium." (PMID 21624123, 2011). "This analysis, allowed us to identify a highly significant group of 29 genes whose level of expression was significantly mediated by Rac1 and/or Cdc42 activity, only 14 of which have previously been reported to play a role in cancer." (PMID 20067638, 2010). "Microarray analysis revealed that the expression of 29 genes was dependent on Rac1 and Cdc42, many of which are known to play a role in cancer." (PMID 20067638, 2010). "As well as our findings in patients with UC-UUT, overexpression of Rac1 and Pak1 has been reported in several other human cancers." (PMID 20426825, 2010). "Rac1 can also contribute to cancer cell invasion by regulating the production of MMPs and their natural inhibitors, the tissue-specific inhibitors of MMP (TIMPs)." (PMID 20822528, 2010). "Alternative splicing regulates cancer-related properties of Rac1, leading to synthesis of constitutively active Rac1b, whose expression is upregulated in cancers." (PMID 21082031, 2010).
cancer (continued). "Rac1 and Pak1 have recently been shown to be key regulators of cancer cell signaling networks, and there are several lines of evidence linking Rac1 and Pak1 to the acquisition of migratory, invasive, and metastatic phenotypes." (PMID 20426825, 2010). "The suppressive effect on cell migration by Cyr61 knockdown was also largely due to the decreased level of activated Rac1, which has also been shown important in cell migration in some other kinds of cancer cells." (PMID 18941464, 2008). "Rac1 is often overexpressed or over-activated in several cancers, promoting cell invasion, metastasis, and angiogenesis; however, the expression of Rac1 in RMS was previously unknown." (PMID 40076757, 2025). "As of today, RAC1 gene copy alteration remains undruggable in human cancer, including HNSCC." (PMID 39941730, 2025). "To investigate whether RAC1 can accurately diagnose tumors, we conducted ROC curve analyses and calculated the AUC values for RAC1 at the pan-cancer level." (PMID 39898257, 2025). "Overall, Rac1 is emerging as a promising therapeutic biomarker in selected cancers." (PMID 41360259, 2025). "The integrated analysis of RAC1 expression across different clinical stages (I, II, III, and IV) at the pan-cancer level reveals a positive correlation between RAC1 expression and clinical stages in 7 cancers, including ACC, BRCA, COAD, KIRC, LIHC, PAAD, and READ." (PMID 39898257, 2025). "Based on the results described here, future therapeutic strategies should consider the use of RAC1 inhibitors in combination with existing anti-cancer therapies, to reduce tumor development and metastasis, as well as to decrease resistance to anti-cancer therapies." (PMID 40633540, 2025). "Additionally, univariate Cox regression analysis of DSS and PFI data at the pan-cancer level was conducted to further evaluate the prognostic value of RAC1." (PMID 39898257, 2025). "Our study identified a significant negative correlation between RAC1 expression and B cell infiltration across cancer types, suggesting that RAC1 may act as a regulator of B cell activity." (PMID 39898257, 2025). "MEG3 suppresses cancer cell invasion and migration by inhibiting Rac1 expression via its 3′UTR." (PMID 41150811, 2025). "The correlation between biomarker expression and cancer stage, particularly the higher expression levels in advanced‐stage tumors, suggests that RhoA and Rac1 could serve as reliable indicators of tumor progression." (PMID 39887960, 2025). "Our study demonstrates that mechanical stretching significantly upregulates the expression of the protein biomarkers RhoA and Rac1 in clinical cancer samples and cancer cells, with a clear correlation between increased biomarker levels and advanced cancer stages." (PMID 39887960, 2025). "This also suggests that drugs targeting RAC1 may be useful in combination with classic chemo- and radiotherapies for the treatment of numerous aggressive cancers." (PMID 40633540, 2025). "As of today, RAC1 aberrations remain chemically undruggable for any human cancers, including HNSCC." (PMID 39941730, 2025). "Rac1, a member of the Rho GTPase family, represents a crucially deregulated signaling player leading to tumor progression, particularly in the metastatic spread of cancer cells." (PMID 40894927, 2025). "Notably, RAC1 was predominantly expressed in epithelial cells, malignant cells, and monocytes/macrophages (Mono/Macro cells) across these cancer types." (PMID 39898257, 2025). "However, despite RAC1 being a potent biomarker for cancer, our understanding of its role in pan-cancers as well as immune microenvironment remodeling is not yet comprehensive." (PMID 39898257, 2025). "Among which, M-Ras, H-Ras, and R-Ras are classical members of Ras family cancer therapy; Rap1 belongs to the Rap subfamily, which is involved in integrin activation and plays key roles in cell adhesion; and Rac1 is an important member of the Rho family that regulates cytoskeleton dynamics." (PMID 41360259, 2025).
cancer (continued). "Therefore, there is an urgent need to investigate the function of RAC1 across various types of cancers." (PMID 39898257, 2025). "Rac1 is often deregulated in pathological conditions, including neurological diseases and cancer." (PMID 40894927, 2025). "Notably, Rac1 expression in clinical cancer samples exhibited a marked increase following mechanical stretching." (PMID 39887960, 2025). "To more specifically investigate the impact of RAC1 on the immune microenvironment, we analyzed the relationship between RAC1 expression and the activity of immune checkpoints and immunosuppressive factors at the pan-cancer level." (PMID 39898257, 2025). "Deregulated expression or activation of RAC1 signaling leads to the generation of anarchic cellular responses that contribute to pathological processes, in particular cancers, by promoting neoplastic transformation, progression, invasion, and metastatic dissemination." (PMID 40633540, 2025). "Rac1 is often overactive in cancers, driving metastasis by enhancing cell motility and invasion." (PMID 39953622, 2025). "We then analyzed the effects of either treatment on the signaling pathways downstream to PI3K which are commonly triggered by integrins in cancer cells, focusing on Akt and the small GTPase Rac-1, which we already showed to be preferentially activated downstream to hERG1." (PMID 39900574, 2025). "Moreover, given the function of signal transduction from the external cell to the actin cytoskeleton, RAC1 plays an important role in cell invasion/metastasis of several cancers." (PMID 40362690, 2025). "After receiving upstream signals from Rac1, the Scar/Wave complex regulates F-actin cytoskeleton polymerization by activating the Arp2/3 complex, thus forming actin-based membrane processes, which are essential for cell migration and cancer cell invasion." (PMID 40141305, 2025). "The small GTPase RAC1 undergoes splicing changes in multiple cancers." (PMID 40548642, 2025). "Upon activation, Src kinase interacts with various substrates, initiates downstream signaling which involves p130Cas, oncogenic signaling pathways that promotes Src-mediated cancer cell invasion and migration by modulating cytoskeleton organization through the activation of Rac1." (PMID 39045054, 2024). "Rac1 is required for the G1-S phase transition in proliferating cancer cells, so we investigated whether there was decreased S phase entry and DNA synthesis in Rac1-null CDs." (PMID 38324689, 2024). "Nevertheless, although Rac1 plays an important role in the development of cancer, there is a lack of clinical studies associated with Rac1." (PMID 38791951, 2024). "Inhibition of PAK1, the primary downstream target of Rac1 responsible for vimentin Ser38 phosphorylation greatly reduced metastasis, highlighting a promising potential for developing drugs targeting this function for cancer treatment." (PMID 38915055, 2024). "RAC1 expression has been found to be correlated with worse prognosis for many cancers." (PMID 39001533, 2024). "Rac1 also has a role in cancer initiation, progression, invasion, and metastasis." (PMID 38362155, 2024). "The regulation of invadopodium formation via the Rac1-dependent pathway may also play a role in the exosome biogenesis process in cancer cells." (PMID 39062561, 2024). "Overall, our results indicate an essential role of ITGAV/RAC1 signaling in cancer cell maintenance." (PMID 38316881, 2024). "As such, Rac1 represents a potential therapeutic target for cancer metastasis." (PMID 38191532, 2024). "Moreover, the role of RAC1 in cancer cell proliferation, migration, and drug resistance has been extensively documented in many cancer studies." (PMID 38378644, 2024). "To date, there are no established standard treatments for cancers that harbour an additional RAC1 mutation or for RAC1-mediated drug resistance." (PMID 40396280, 2024). "Endogenous PREX1 knockdown reduces Rac1 activity and cancer cell invasion in SCC cells." (PMID 38191532, 2024).
cancer (continued). "al found that, the transmembrane protein coiled-coil domain containing 25 (CCDC25) functions as a receptor for NETs-DNA on the surface of cancer cells, activating the ILK/β-parvin/RAC1 pathway and enhancing cancer cell motility by sensing extracellular NETs-DNA." (PMID 38664728, 2024). "Based on these chemical features, Rhein may effectively bind to and inhibit the activity of Rac1, thereby modulating biological processes and potentially serving as a therapeutic agent in cancer diseases." (PMID 39161777, 2024). "Additionally, ITGB6 has been shown to promote the acquisition of stem-like properties in cancer cells, allowing them to resist chemotherapy and evade immune surveillance, and this is also mediated through Rac1 signaling." (PMID 38344200, 2024). "In parallel, as our studies highlighted a prominent role of the Rho GTPase Rac1 on 5-FU-resistance modulation, we decided to explore the effects of 1A-116, a novel Rac1 inhibitor previously reported to be promising to treat other cancer types." (PMID 39513883, 2024). "RAC1 was more highly expressed in 28 different types of cancer, especially PAAD." (PMID 38968580, 2024). "Of these three signalling pathways, RAC1 has been found to be hyperactivated in human cancers and promotes tumour initiation, progression, and metastatic dissemination, and may be consistent with a link between PCOS and EC." (PMID 37737665, 2023). "Understanding the role and the regulatory mechanism of Rac1 in cell migration can provide fundamental insights into Rac1-related cancer progression and further help us to develop novel intervention strategies for cancer therapy in clinic." (PMID 37049739, 2023). "Much is known about Rac1/cdc42 in cancers such as breast and pancreatic." (PMID 37908840, 2023). "On the other hand, cancer samples from TCGA Pan Cancer Atlas Studies harboring high CN increase in RAC1 gene display enhanced expression of CBX3 RNAs, thus further confirming that gene amplification of RAC1 and CBX3 leads to an increase of CBX3 and RAC1 mRNAs, respectively in human cancers." (PMID 37633946, 2023). "Overactivation of Rac1/PAK1 signaling is a common feature of multiple types of cancer." (PMID 36951547, 2023). "In addition, rhein can inhibits the migration and invasion of cancer cells, via Rac1/ROS/MAPK signaling pathway." (PMID 36969843, 2023). "We can thus argue that the co-occurrence of CBX3 and RAC1 gene amplification might be a way to increase RAC1 and CBX3 expression during cancer development, two well-known proteins that have been linked to cancer growth and proliferation when overexpressed." (PMID 37633946, 2023). "The identification of P-Rex1 as a NRBP1 binding partner sheds new light on the oncogenic role of NRBP1, not only due to the well-established roles of Rac1/Cdc42 in human cancer, but also because P-Rex1 has recently emerged as an important oncogene in its own right." (PMID 36693952, 2023). "Additionally, Rac1 is commonly hyper-expressed in some types of cancer, including urothelial carcinoma." (PMID 37221195, 2023). "Rac1-Scar/Wave-Arp2/3 is a key target for preventing or inhibiting cancer invasion and metastasis." (PMID 37049739, 2023). "The pharmacological role of Ketorolac in cancer is best viewed through two distinct classes of targets COX and Rac-1/Cdc42, which may contribute to the anti-inflammatory and anti-cancer activity." (PMID 37024613, 2023). "As epidermal growth factor receptor (EGFR), Vav1, RhoA, Rac1, and BPGAP1 are all associated with cancer metastasis, BPGAP1 could provide a crucial checkpoint for the EGFR-BPGAP1-Vav1-Rac1-RhoA signaling axis for cancer intervention." (PMID 36598812, 2023). "Collectively, our findings indicate that the concomitant overexpression of both EGFR, CBX3 and RAC1 may be an extremely unfavorable general prognosis marker in human cancer." (PMID 37633946, 2023).
cancer (continued). "Rac GTPases (Rac1, Rac2, and Rac3) have been recognized as important nodes in signalling networks, that control malignant transformation and the metastatic dissemination of cancer cells." (PMID 37316799, 2023). "RAC1 is listed as a significant member of the Rho GTPases, which are involved in the tumor cell cycle, invasion, proliferation, apoptosis, angiogenesis, and migration, and are viewed as promising targets for preventing and treating cancers." (PMID 37620594, 2023). "This may also be an isoform dependent effect because cancer cells express Rac1 and Rac3, while hematopoietic cells express Rac2." (PMID 37397366, 2023). "Next, we set out to check whether the co-amplification of CBX3 with either EGFR or RAC1 genes might affect cancer aggressiveness and patient lifespan." (PMID 37633946, 2023). "As a key molecule in regulating cell migration, Rac1 participates in signal transduction from the external cell to the actin cytoskeleton and promotes the establishment of cell polarity which plays an important role in cancer cell invasion/metastasis." (PMID 37049739, 2023). "Next, we found copy number variations of MAP2K6, SHC1, and RAC1 in most cancer tissues." (PMID 36969076, 2023). "Since hAM preparations strongly reduced the migration of cancer urothelial cells, we further investigated their effect on the expression of key components required for efficient cell migration, such as cortactin, RhoA, RhoC, Cdc42 and Rac1." (PMID 37932474, 2023). "Rac1 also functions in human carcinoma cells to downregulate contractile myosin and make cells more deformable; Rac1 dominant-active cells outcompete Rac1-deficient mutant cells via entosis while its depletion causes cells to be stiffer and lose out to more deformable cells." (PMID 38106045, 2023). "Rac1 inhibitors could be useful to combat these different pathologies, in particular, to tackle OAB associated with cancer." (PMID 35740379, 2022). "In addition, FDPS is a critical gene involved in CBS and is required for the isoprenylation of Rho GTPase Rac1, which drives K-Ras-driven cancers." (PMID 34971971, 2022). "In particular, the suppression of MVA disrupts prenylation of the small GTPase Rac1 and induces cancer cell actin filament exposure, which can be recognized by c-type lectin domain family 9 member A (CLEC9A) specifically expressed on cDC1s and thus activating infiltrating T cells." (PMID 36003368, 2022). "Likewise, CSDE1 acts as a proto-oncogene by regulating c-myc, c-fos, RAC1, and vimentin expression and promotes metastasis and invasion in cancer." (PMID 35490208, 2022). "Interestingly, P-Rex1/Rac1 is known to cooperate with PDGFRβ in cancer cell invasion, which, along with neointimal hyperplasia, are classical examples of dysregulated cellular migration." (PMID 35241778, 2022). "HGF-related actin rearrangement, which is linked to cancer cell morphogenesis and metastasis, is primarily regulated by small GTPase activity, especially RhoA, Rac1, and Cdc42; however, various types of cancer cells use distinct signaling pathways in response to HGF to activate small GTPase." (PMID 35630066, 2022). "To discern the molecular underpinnings of our observed changes in stemness and invasion due to altered SNHG1 expression, we performed Western blotting using antibodies against several proteins implicated in cancer cell stemness and invasion, including SOX2, OCT4, CD133, and Rac1." (PMID 36077697, 2022). "In the current study, we found that whencircBRWD3 expression was inhibited, the cell proliferation and metastasis of cancer were suppressed, a phenomenon that could be reversed by RAC1 overexpression." (PMID 36443711, 2022). "Small GTPases, such as Rac1 and Rho-A are well described as mediators of migration through cytoskeletal remodeling and have critical roles in the invasive and metastatic behavior of cancer cells." (PMID 36207615, 2022). "Rac1 can affect the expression of cyclin and then regulate the proliferation of cancer cells." (PMID 35682879, 2022).